INS (insulin)
Diseases named in the same sentence as INS in open-access papers (continued):
Sharing a sentence is not in itself a finding about the gene and the disease.
Hyperglycemia (continued). "Herein, a novel self‐crosslinkable and glucose‐responsive polymer‐based microneedle patch (MN) is designed to deliver insulin at hyperglycemia." (PMID 37718654, 2023). "We and others have shown that chronic exposure of β-cells to hyperglycemia deteriorates insulin secretion and induces apoptosis." (PMID 37008937, 2023). "It is a chronic metabolic disorder characterized by high blood glucose levels (hyperglycaemia) due to inadequate insulin production, impaired insulin action, or a combination of these." (PMID 37759802, 2023). "In people with T1D, the body can’t increase insulin production in response, which leads to hyperglycemia." (PMID 36964201, 2023). "The upregulation of these pathways in our HG treated group suggests a possible attempt of these cells to maintain appropriate β-cell mass, insulin production and survival in response to hyperglycemia." (PMID 36709757, 2023). "Decreased sensitivity to insulin leads to hyperinsulinemia and hyperglycemia but reduced cellular glucose uptake." (PMID 37760862, 2023). "Deletion of Dpy30 from maturing beta cells using Ins1Cre caused reduction of H3K4 methylation in islets by 5 weeks of age, leading to hyperglycaemia, impaired glucose tolerance and reduced serum insulin levels." (PMID 36912927, 2023). "Lactococcus lactis was reported to positively influence hyperglycaemia reduction, glucose tolerance improvement, and insulin secretion enhancement." (PMID 37628624, 2023). "Previous studies have shown that defective insulin secretion in cystic fibrosis affects growth before hyperglycemia occurs, which is also confirmed by another study." (PMID 36978136, 2023). "In a study, hyperglycemia control (for blood glucose level 80 - 140 mg/dl) using once-daily glargine insulin versus twice-daily NPH/regular insulin in patients after cardiovascular surgery was evaluated." (PMID 37342663, 2023). "The extract reduced the bodyweight gain and fats, and hyperglycemia, and it improved insulin sensitivity compared to the HFD-induced obese group that was not treated with the extract." (PMID 37103396, 2023). "In insulin-resistant condition, the biological action of insulin to maintain glucose and lipid homeostasis is compromised that gradually leads to the onset of hyperglycemia and hyperlipidemia with manifestations of T2D." (PMID 36718668, 2023). "Although the hyperglycemia was mild to moderate, it suggests the need for stronger dietary recommendations, blood glucose monitoring, and optimization of insulin therapy after discharge." (PMID 38993859, 2023). "Hyperglycemia, hyperinsulinemia, elevated fatty acids, and impaired insulin signaling are the primary initiators of diabetic cardiomyopathy." (PMID 36979641, 2023). "Glycemic levels rise to levels compatible with DM2 when the mismatch between insulin demand and production persists, called hyperglycemia." (PMID 37346347, 2023). "Both peripheral IR and insufficient insulin release from pancreatic islet β-cells induce hyperglycemia and, therefore, increase insulin demand." (PMID 36900929, 2023). "What’s more, it has been widely documented that Agrimonia pilosa Ledeb provided a considerable resistance to hyperglycemia and IR in insulin incubated-HepG2 cells and high-fat diet-fed rats." (PMID 37710214, 2023). "T2DM is a complicated chronic metabolic disorder characterized by hyperglycemia, which often results from defects in insulin secretion, insulin resistance, or both." (PMID 37768924, 2023). "In individuals with CF, the initial phase of insulin secretion, which is dependent on depolarization, experiences a delay, resulting in postprandial hyperglycemia." (PMID 38136081, 2023). "More importantly, we observed increased expression of adiponectin exclusively expressed in the adipose tissue, which improves hyperglycemia by decreasing plasma glucose levels, and improves insulin sensitivity in mice." (PMID 37573386, 2023).
Hyperglycemia (continued). "When compared to the situation before the COVID-19 pandemic, children with new-onset T1D had higher hyperglycaemia and glycosylated hemoglobin (HbA1c) and a higher insulin requirement." (PMID 37241176, 2023). "However, because one such method of administration does not directly correspond to the glucose concentrations in the blood and may fail to reduce hyperglycemia or cause hypoglycemia, the delivery of insulin in a glucose-dependent manner has been researched intensely in the present and past." (PMID 36676521, 2023). "In turn, this hyperglycemia induces hyperinsulinemia (high insulin production) in the fetus, subsequently increasing the birth weight of the infant." (PMID 37900684, 2023). "This setting significantly reduces the potential for insulin overdose when hyperglycemia is corrected by the user." (PMID 37908748, 2023). "The reported adverse effects of high doses of insulin are hypoglycemia, hyperglycemia, hypokalemia, hypomagnesemia and hypophosphatemia." (PMID 37505522, 2023). "Chronic exposure to a high level of glucose impairs the functions of beta cells and insulin and contributes to the development of hyperglycaemia, which leads to insulin resistance." (PMID 36829539, 2023). "The severe hyperglycaemia on admission itself is a marker of dysregulated glucose-insulin metabolism in patients with COVID-19 infections." (PMID 38192935, 2023). "PQQ, as a newly discovered oxidoreductase coenzyme, performed forceful therapeutic promise effectively to lose weight, combating hyperglycemia, hyperlipemia, and increased insulin levels." (PMID 37935689, 2023). "Reintroduction of adipsin into diabetic mice alleviates hyperglycemia by enhancing insulin secretion." (PMID 37761031, 2023). "Adverse effects of treatment included mouth ulcerations which spontaneously resolved, transient hyperglycemia in one patient, and increased insulin requirements for one diabetic patient." (PMID 37313059, 2023). "A complex interplay between counter regulatory hormones (catecholamines, glucagon, glucocorticoids, and growth hormone), circulating cytokines and peripheral insulin resistance plays a role in the genesis of stress hyperglycemia." (PMID 37120562, 2023). "Type 1 diabetes is a chronic auto-immune disease characterized by deterioration of insulin-producing beta cells in the pancreas, leading to insulin depletion and hyperglycemia." (PMID 36754894, 2023). "The combinational use of AGS inhibitors with insulin, metformin, and sulfonylureas is an intervention for uncontrolled hyperglycemia recommended by the International Diabetes Federation." (PMID 37175232, 2023). "Clock mutant mice show hyperglycemia, decreased levels of expression, and phase shifts of RNA oscillation of genes that participated in glucose sensing, insulin signaling, islet growth, and development." (PMID 38089624, 2023). "Disturbances associated with IFG result in an increase in hepatic glucose production and fasting hyperglycemia, but during activity, its plasma concentration gradually decreases as it is used as energy by muscles that remain insulin sensitive." (PMID 37049479, 2023). "DM is a chronic metabolic disease characterized by high sugar levels (hyperglycemia) due to impairment of insulin secretion, cellular resistance to insulin or both." (PMID 37822815, 2023). "When tissues are insulin-resistant, glucose is unable to enter cells and remains in the blood, inducing hyperglycemia." (PMID 38192911, 2023). "Phenolic compounds from R. scutatus, R. dentatus, and R. patientia lowered hyperglycemia and improved the glucose tolerance, insulin sensitivity, and even the lipid profile and the hepatoprotective effect in diabetic rats." (PMID 37570730, 2023). "National guidelines recommend more frequent CBG monitoring and the use of insulin to treat hyperglycemia." (PMID 37893045, 2023).
Hyperglycemia (continued). "These pumps allow patients to control their insulin dosages by administering controlled amounts of insulin subcutaneously, and thus it helps prevent the occurence of both hypoglycemia and hyperglycemia." (PMID 37915365, 2023). "In many patients, reduced insulin secretion and impaired insulin movement coexist, and it is tough to inform which condition, if either, is the essential supply of hyperglycemia." (PMID 37287539, 2023). "Studies have shown that hyperglycemia can modulate insulin signaling by impairing insulin receptor activity and Pi3K/AKT signaling." (PMID 36722656, 2023). "In this period, the AHCL system was providing increased basal insulin delivery, in combination with automatic correction boluses to treat this hyperglycaemia." (PMID 37864225, 2023). "If the pancreatic beta cells are unable to secrete sufficient insulin to compensate for the reduced insulin sensitivity (termed beta cell dysfunction), hyperglycemia ensues, leading to glucose intolerance and eventually T2D." (PMID 37396595, 2023). "As a consequence, hyperglycemia occurs even though the insulin circulating in the blood is at the physiological level." (PMID 37346355, 2023). "TBFs have been shown to have significant antidiabetic effects, as evidenced by the marked reductions in serum glucose and insulin levels, improved insulin sensitivity, and alleviation of hyperglycaemia-induced oxidative stress." (PMID 38092733, 2023). "The exact mechanisms involved in the effect of chrysin on insulin sensitivity and hyperglycemia are unclear." (PMID 36838721, 2023). "The HIV accessory protein, viral protein R, and cART combination have been reported to affect insulin sensitivity by regulating hepatic lipid metabolism, leading to hyperglycemia and dyslipidemia." (PMID 36846379, 2023). "DM sufferers in a physiological and emotional stress state will trigger hyperglycemia, thereby enhancing glucose production by the liver and disrupting the use of glucose in muscle and fat tissue by opposing the action of insulin." (PMID 37990213, 2023). "In patients with sepsis, hyperglycemia typically arises from the activation of proinflammatory mediators and the release of counterregulatory hormones, resulting in heightened peripheral insulin resistance and increased hepatic gluconeogenesis." (PMID 37764757, 2023). "T1DM is an autoimmune condition that destroys insulin-producing beta cells, leading to hyperglycemia." (PMID 36835260, 2023). "After a two-week treatment, NPH insulin alone was unable to achieve normoglycemia but did effectively reduce extreme hyperglycemia in the diabetic rats." (PMID 37760247, 2023). "Can HFD-resistant HK2 expression in adipose tissue prevent diet-induced insulin insensitivity and hyperglycemia?" (PMID 36920797, 2023). "Peroxisome proliferator-activated receptor (PPAR)γ agonists, especially the representative compounds, thiazolidinediones (TZDs), alleviate hyperglycemia by effectively increasing glucose uptake and insulin sensitivity and improving insulin resistance." (PMID 38004168, 2023). "Due to the absolute deficiency of insulin in patients with type 1 diabetes, their insulin regimen covers the basal requirement as well as anticipated nutritional and unanticipated accidental hyperglycemia." (PMID 37120562, 2023). "Maternal hyperglycemia induces fetal hyperglycemia, stimulating pancreatic activity resulting in hypertrophy, hyperplasia, and increased insulin secretion." (PMID 37892622, 2023). "Unexplained hyperglycemia can pose a significant challenge to the success of insulin infusion therapy." (PMID 38093983, 2023). "The enhanced increase in the insulin/glucagon ratio during hyperglycemia leads to decreased fasting and postprandial hepatic glucose production and reduced glycemia." (PMID 38057844, 2023).
Hyperglycemia (continued). "Delayed conditional deletion of Isl1 in Pdx1lateCre;Isl1f/f during the secondary transition results in a severe hyperglycemia phenotype due to a significant reduction in insulin+, glucagon+, and somatostatin+ endocrine cells." (PMID 36899442, 2023). "By entering β cells through the glucose transporter 2 (GLUT2), STZ reduces insulin production and results in hyperglycemia." (PMID 37333473, 2023). "Compared with non-diabetic controls, diabetic mice showed decreased body weight, hyperglycemia, and elevated water and food consumption, all of which were normalized by insulin supplementation." (PMID 36782199, 2023). "The only minor adverse side effect of stress-dose glucocorticoid management in AI patients is hyperglycemia, which necessitates intravenous insulin infusion." (PMID 36676776, 2023). "Chronic hyperglycemia gradually decreases insulin biosynthesis and secretion which is accompanied by reduced expression of very important insulin gene transcription factors MafA and PDX-1." (PMID 37720599, 2023). "Administration of adipsin in db/db mice was found to improve hyperglycemia, to increase insulin levels, and to preserve β-cell function by blocking dedifferentiation and death." (PMID 37008937, 2023). "Once taken up by β-cells, STZ initiates oxidative stress and DNA alkylation, ultimately leading to pancreatic β-cell necrosis, reduced insulin production, and hyperglycemia." (PMID 38004453, 2023). "Chronic hyperglycemia induces oxidative stress that promotes the destruction of insulin-producing pancreatic β-cells, worsening hyperglycemia." (PMID 37755075, 2023). "The result of reduced tissue sensitivity to insulin is hyperglycemia and lipid disorders (mainly hypertriglyceridemia)." (PMID 37887427, 2023). "Central injection of apelin in obese diabetic mice induced hyperglycemia, while there was a slight change in insulin level." (PMID 37424869, 2023). "The postulated explanation (with a prescription of a higher amount of macronutrients during the first seven days) for hyperglycemia and treatment with insulin in the less mature and lighter infants cannot be supported by the data given." (PMID 37892314, 2023). "During the clamp, EGP suppression by hyperglycemia and endogenous insulin secretion was impaired so that at the end of the clamp EGP was higher in the presence of exendin 9-39 (2.9 ± 0.4 μmol/kg/min versus 5.7 ± 0.3 μmol/kg/min, P < 0.01)." (PMID 37751301, 2023). "T1DM is caused by autoimmune destruction of β-cells in the pancreas, resulting in hyperglycemia and a progressive decline in insulin secretion." (PMID 36756089, 2023). "Hyperglycemia is accompanied by insulin resistance and high blood viscosity, which increases shear stress on the vessel wall." (PMID 37607768, 2023). "Similar to previous studies, we observed that blood glucose drastically increases, paralleled by increasing circulating insulin to attempt to compensate for the persistent hyperglycemia as the rats progress from a healthy to prediabetic phenotype." (PMID 37233701, 2023). "T2DM is a chronic metabolic disorder characterized by a condition of hyperglycemia that arises from impaired insulin secretion and/or from peripheral resistance to insulin action." (PMID 38137721, 2023). "T2D is characterized by prolonged hyperglycemia due to dysfunction in insulin secretion and cells’ failure to respond to insulin action." (PMID 38203195, 2023). "As shown during the glucose tolerance tests, mice exposed to particulate air pollutants via gavage were unable to mount a compensatory increase in insulin to counter-regulate hyperglycemia." (PMID 36895000, 2023). "The relative contribution of basal hyperglycemia increased gradually with HbA1c increasing and predominant strategy for insulin titration among T1D is different among different levels of glycemic control." (PMID 37143431, 2023).
Hyperglycemia (continued). "There is also evidence that in patients who are diagnosed with severe hyperglycaemia (HbA1c > 9%–10%), insulin can control gluco‐ and lipo‐toxicity within a few days of therapy." (PMID 36722454, 2023). "T1DM is a chronic autoimmune disease that is characterized by the T-cell-mediated destruction of insulin-producing β cells in the pancreatic islets, leading to a decrease in insulin levels in the body and ultimately leading to hyperglycemia in patients." (PMID 38139373, 2023). "Glucagon and insulin dual-hormone systems, without meal announcements or with simple meal announcements, have been found to reduce both hyperglycaemia and hypoglycaemia compared to conventional insulin pump therapy." (PMID 37289734, 2023). "At baseline, prior to rtCGM initiation, primary reasons for ER visits were hyperglycemia (56%), hypoglycemia (22%), 11% illness and hyperglycemia, and 11% out of insulin." (PMID 40303275, 2023). "To conclude, hyperglycemia is prevalent in patients with severe COVID-19 and relates to inadequate beta cell response to match insulin resistance in acute disease." (PMID 37460458, 2023). "By 8 years old glucose concentrations began dropping overnight despite interruption of basal insulin infusion, while spikes of hyperglycaemia were observed postprandially, and HbA1c rose to 68 mmol/mol (8.4%)." (PMID 37562398, 2023). "Hepatic BACH1 knockdown ameliorates hyperglycemia and improves insulin sensitivity in diabetic male mice." (PMID 38129407, 2023). "As anticipated, both dapagliflozin and insulin treatments lowered hyperglycemia in the treated diabetic mice groups when compared to the untreated diabetic mice." (PMID 36986825, 2023). "The prevalent use of lipids at the expense of glucose leads to a reduction of glucose uptake and glycogen synthesis rate in skeletal muscles; this induces a state of chronic hyperglycaemia (glucotoxicity) that further impairs insulin sensitivity." (PMID 38136211, 2023). "The strawberry fruit extract showed positive results against these diabetic parameters and reduced the severity of hyperglycemia by enhancing plasma insulin levels." (PMID 37569180, 2023). "The reduced insulin-dependent inhibition of hepatic glucose production in turn intensifies hyperglycemia in obese Sert-/- mice." (PMID 37520561, 2023). "As expected, both strains were insulin resistant as indicated by marked hyperglycemia and hyperinsulinemia as well as a considerably reduced glucose infusion rate (GIR) during the hyperinsulinemic clamp studies compared to the respective wild-type controls." (PMID 37100238, 2023). "Higher resistance to insulin in individuals with a higher BMI‐SDS is supposed to accelerate overt hyperglycemia with an earlier clinical presentation before total beta‐cell loss." (PMID 37572062, 2023). "In this chronic disease, hyperglycemia, that is, increased blood glucose levels, occurs due to insufficient amounts of insulin or ineffective insulin function." (PMID 37367903, 2023). "Owing to its excellent insulin delivery profile at hyperglycemia and capability of preserving the bioactivity of insulin, the proposed MN patch is of great potential for minimally‐invasive administration of insulin, as confirmed via in vivo experiments." (PMID 37718654, 2023). "His hyperglycemia was managed by insulin infusion in the intensive care unit, and he was discharged with home medication of insulin." (PMID 38022276, 2023). "According to previous research, hyperglycemia can be treated by transplanting pancreatic or islet cells to replace cells that have lost function and, therefore, reduce the need for insulin." (PMID 37375806, 2023). "Compared with persistent hyperglycemia, islet β-cell dysfunction and apoptosis increased significantly in the state of blood glucose fluctuation which leading to decrease of insulin secretion." (PMID 36967789, 2023).